IL1R1 (interleukin 1 receptor type 1)
Diseases named in the same sentence as IL1R1 in open-access papers (continued):
Sharing a sentence is not in itself a finding about the gene and the disease.
lung fibrosis (7 papers, 2013 to 2022). "Furthermore, both IL-1α and IL-1β have been shown to be increased in mice following bleomycin challenge and IL-1α-, IL-1β- and IL-1R1-deficient mice are protected from bleomycin-induced pulmonary fibrosis." (PMID 27001429, 2016). "The results also showed that while IL1-R1 signaling is redundant for lung fibrosis, STAT6 mediated Th2 response is essential in the process of fibrosis induced by biopersistent MWCNTs." (PMID 28903780, 2017). "We exposed IL-1R1 deficient mice or STAT6 deficient mice to Mitsui XNRi-7 (Mitsui-7), a MWCNT variant known to induce lung fibrosis in experimental rodents." (PMID 28903780, 2017). "Interleukin 1 receptor 1 (IL-1R1) signaling is critical for lung fibrosis and inflammation of mice." (PMID 36133309, 2022). "Uric acid, which has been demonstrated to play an important role in lung fibrosis in mice via an inflammasome- and IL-1R1-dependent pathway, has also been reported to be elevated in BAL of healthy smokers compared to healthy non-smokers as well as COPD patients who smoke compared to healthy smokers." (PMID 27001429, 2016). "While expression of genes coding for soluble mediators (e.g. cytokines) were unchanged, receptors for several mediators known to participate in lung fibrosis were up-regulated (CCR2, FGFR2, FLT1, IGF1R, IL1R1 and IL6R)." (PMID 23844029, 2013).
steatosis (7 papers, 2014 to 2025). Increased lipid within the cytoplasm of cells. "Marked differences between the WT and IL‐1R1 knockout were only seen at the level of microvesicular steatosis that was significantly less pronounced in the Il1r1Hep−/– mice on HFD." (PMID 36101976, 2022). "The liver of IL-1R1 KO mice treated with IL-1Ra ASO was significantly lighter than control treated IL-1R1 KO mice and showed less steatosis and significantly reduced inflammation." (PMID 25244011, 2014).
allergic disease (6 papers, 2014 to 2025). An immune response that occurs following re-exposure to an innocuous antigen, and that requires the presence of existing antibodies against that antigen. "Third, phenotype scanning suggested that IL1R1 (rs7588201) is associated with allergic rhinitis (AR), eczema, and allergic disease; ECM1 in plasma (rs13294) is associated with atopic dermatitis." (PMID 37809092, 2023). "The results demonstrated a significant association of TNFAIP3, IL1RL2, IL1R1, IL6R, KYNU, and ITPKA with allergic diseases in both cohorts, further supporting the reliability of the potential drug targets identified in this study." (PMID 38573314, 2024). "First of all, our research shows that the expression level of IL1R1 protein is related to the occurrence of allergic diseases." (PMID 38573314, 2024). "Next, we have been further verified in two large independent external cohorts, providing further evidence for IL1R1 as a potential target for allergic diseases." (PMID 38573314, 2024). "In conclusion, IL1R1 could be a potential therapeutic target for allergic diseases." (PMID 38573314, 2024). "Indeed, the connection between allergy and Interleukin 1 receptor-like-1 (IL1R1) is already known." (PMID 25477900, 2014).
Alzheimer disease (6 papers, 2014 to 2025). A progressive, neurodegenerative disease characterized by loss of function and death of nerve cells in several areas of the brain leading to loss of cognitive function such as memory and language. "However, we cannot draw broader conclusions about the role of IL-1β or IL-1R1 signaling in Alzheimer’s disease." (PMID 41191631, 2025).
chronic obstructive pulmonary disease (6 papers, 2011 to 2025). A chronic and progressive lung disorder characterized by the loss of elasticity of the bronchial tree and the air sacs, destruction of the air sacs wall, thickening of the bronchial wall, and mucous accumulation in the bronchial tree. "Interleukin-1 receptor 1 (IL-1R1) inhibition is a potential strategy for treating patients with chronic obstructive pulmonary disease (COPD)." (PMID 28793896, 2017).
experimental autoimmune encephalomyelitis (6 papers, 2016 to 2024). An autoimmune demyelinating disease of the central nervous system that is produced experimentally in animals by the injection of homogenized brain or spinal cord in Freund's adjuvant. "IL-1R signaling in T cells has been shown to be critical for the generation of Th17 cells as mice deficient in IL-1R1 have a defect in the generation of Th17 responses in an experimental autoimmune encephalomyelitis (EAE) model with an associated reduction in disease severity." (PMID 26978520, 2016). "Interleukin-1 receptor-like 1 (IL1R1) is an immune-related gene and has been involved in the pathology of multiple sclerosis and experimental autoimmune encephalomyelitis." (PMID 37061663, 2023). "IL-1R1, as a kind of inflammatory factor and transmitter, plays a role in many neurological diseases such as mild closed-head injury, genotype-dependent glioblastoma, postoperative cognitive dysfunction, seizures, and experimental autoimmune encephalomyelitis." (PMID 39211643, 2024). "Addition of exogenous IL-1β to Th cell cultures enhanced in vitro Th17 cell differentiation and IL-1R1-deficient T cells failed to induce Th17-driven disease in murine experimental autoimmune encephalomyelitis (EAE)." (PMID 36389679, 2022). "In previous studies, our group as well as others have reported the importance of endothelial IL-1R1 signaling in the neuroinflammatory processes taking place at the blood-brain barrier (BBB) and BSCB in the experimental autoimmune encephalomyelitis (EAE) mouse model of multiple sclerosis." (PMID 36184639, 2022).
glioblastoma (6 papers, 2015 to 2024). The most malignant astrocytic tumor (WHO grade IV). "Consistently, the MLC proliferation and the expression of IL-6 and IL1R1 were promoted by incubation with conditioned medium from parental glioblastoma cells transfected with siCXCR7." (PMID 38898023, 2024). "We also noticed that the transcription of key genes involved in inflammation, proliferation, angiogenesis and extracellular matrix remodelling (including MMP2, HIF1A, IL1B, IL1A, IL1R1, MMP2, VEGFA), processes vital to glioblastoma development, were down-regulated by RND3 knock-down." (PMID 26132659, 2015).
Hepatic fibrosis (6 papers, 2015 to 2022). The presence of excessive fibrous connective tissue in the liver. "Ten DEGs including PDGFra, PDGFrb, PDGFb, PDGFd, COL1A1, COL1A2, COL5A2, ITGA5, THBS1 and IL1R1, closely related to liver fibrosis, were chosen for the real-time qRT-PCR analysis." (PMID 26691002, 2015). "IL1R1 is overexpressed in some liver diseases, such as ALI, liver fibrosis, and liver cancer." (PMID 36120318, 2022).
Insulin resistance (6 papers, 2014 to 2025). Increased resistance towards insulin, that is, diminished effectiveness of insulin in reducing blood glucose levels. "The current data highlights that hepatocyte IL‐1R1 contributes to hepatic and extrahepatic insulin resistance." (PMID 36101976, 2022). "In adipose tissue, we detected increases in IL-1α, a key cytokine that signals through the IL-1R1 and likely contributes to inflammatory responses relevant to insulin resistance." (PMID 29038790, 2017). "However, marked improvement of insulin resistance, including improved hyperinsulinemia, HOMA‐IR, Adipo‐IR, and whole‐body glucose sensitivity were detectable in mice lacking IL‐1R1 in hepatocytes." (PMID 36101976, 2022). "However, although hepatocyte‐specific knockout of Il1r1 showed increased basal levels of hepatic SOCS3, we did not observe a spontaneous phenotype of insulin resistance or other metabolic perturbances in the knockout mice." (PMID 36101976, 2022).
myocardial infarction (6 papers, 2015 to 2025). Gross necrosis of the myocardium, as a result of interruption of the blood supply to the area, as in coronary thrombosis. "Recently, it is reported that fibroblast-specific IL-1R1 expression was an important contributor to cardiac remodeling after myocardial infarction." (PMID 35087030, 2022). "It has been hypothesized that IL-1α is released from damaged cardiomyocytes following myocardial infarction (MI) and activates cardiac fibroblasts via its receptor (IL-1R1) to drive the early stages of cardiac remodeling." (PMID 31393855, 2019). "Fibroblast-specific knockout of IL-1R1, but not cardiomyocyte-specific knockout of IL-1α, improved cardiac function and remodeling after myocardial infarction." (PMID 31393855, 2019).
depression (5 papers, 2021 to 2025). "Upon analyzing the diagnostic model, it was revealed that EPAS1 and IL1R1 serve as key biomarkers for OS in depression, with IL1R1 exhibiting the highest diagnostic potential among them." (PMID 40343008, 2025). "The results of the GWAS, published this year, suggest that specific SNPs, including rs2540315 and rs75746675 in the IL-1 receptor gene IL1R1, were associated with a rapid (within 240 min) antidepressant effect of ketamine infusion in patients with treatment-resistant depression." (PMID 37510364, 2023). "In this study, functional enrichment analysis revealed that targets such as CD63, IL17RA, and IL1R1 are involved in depression-related pathways, including the HIF-1, MAPK, and PI3K-Akt signaling pathways." (PMID 40370590, 2025). "This study observed an increased expression of IL1R1 in both peripheral blood and brain tissues of patients with depression, suggesting that IL1R1-mediated signaling may play a role in neuroinflammatory states associated with this condition." (PMID 40343008, 2025). "The findings demonstrate that IL1R1 along with its related genes play a pivotal role in initiating depression onset while also exhibiting potential as emerging biomarkers and therapeutic targets, thereby providing novel insights for scientific research endeavors as well as clinical treatment." (PMID 40343008, 2025). "Similarly, the GSE98793(64 normal individuals and 128 individuals with depression) dataset found a high expression pattern of IL1R1 in peripheral blood." (PMID 40343008, 2025). "Furthermore, we validated this using a Diagnostic Nomogram, where we assessed the probability of a patient being diagnosed with depression by integrating the scores of the IL1R1 and EPAS1 genes." (PMID 40343008, 2025). "Consequently, our analysis uncovers a connection between IL1R1 and lipid regulation, offering valuable insights into the metabolic facets of depression." (PMID 40343008, 2025). "IL-1R1 expression is upregulated in the lymphocytes of patients with MDD, with its mRNA level in lymphocytes serving as a potential biomarker for depression." (PMID 40370590, 2025). "Subsequently, we employed Mendelian randomization analysis to identify IL1R1 and LPO as protective factors against depression." (PMID 40343008, 2025). "Additionally, MRfen analysis suggests that IL1R1 may play a protective role against depression." (PMID 40343008, 2025). "Although several potential drugs targeting CD63, IL17RA, and IL1R1 were identified, limited research exists on their effects on MDD or depression." (PMID 40370590, 2025). "Given the intricate etiology of depression and the lack of effective biomarkers for clinical diagnosis, this study employed multiple data analysis methods to screen and validate genes associated with oxidative stress while delving into the mechanistic role played by IL1R1 gene in depth." (PMID 40343008, 2025).
Granuloma (5 papers, 2013 to 2021). A compact, organized collection of mature mononuclear phagocytes, which may be but is not necessarily accompanied by accessory features such as necrosis. "The possibility cannot be excluded, however, that the cellular components of H. polygyrus–induced granulomas differ in quality between MyD88-deficient and IL-1R1–deficient mice." (PMID 25114104, 2014). "Interestingly, mice singly deficient for IL-1α or for IL-1β developed some granuloma with limited oedema, no necrosis and free alveolar space, thus a much less severe lung pathology than that seen in the absence of both IL-1α and IL-1β or of IL-1R1 at 5 weeks post-infection." (PMID 25400917, 2013).
Hyperglycemia (5 papers, 2016 to 2025). An increased concentration of glucose in the blood. "Using Müller cells known to produce active caspase-1 and IL-1β under hyperglycemic conditions we confirmed that prolonged exposure to hyperglycemia leads to caspase-1/IL-1β/IL-1R1 feedback signaling causing sustained caspase-1 activity." (PMID 39483336, 2024). "To further establish a hyperglycemia-induced caspase-1/IL-1β/IL-1R1 feedback loop we used isolated human Müller cells (hMC)." (PMID 39483336, 2024). "A similar hyperglycemia-mediated caspase-1/IL-1β/IL-1R1 feedback signaling was detected in vitro in human Müller cells which was prevented by treatment with IL-1ra." (PMID 39483336, 2024). "Although our study used Müller cells to demonstrate hyperglycemia-induced caspase-1/IL-1β/IL-1R1 feedback signaling, other retinal cells might be capable of producing similar feedback cycles leading to sustained caspase-1 activation and prolonged IL-1β production." (PMID 39483336, 2024). "Our data also indicate that hyperglycemia induces caspase-1 activation initially but IL-1β sustains caspase-1 activation via caspase-1/IL-1β/IL-1R1 feedback and we identified RIP2 as mediator for both hyperglycemia- and IL-1β-induced caspase-1 activation." (PMID 39483336, 2024). "Il1r1−/− mice were protected from transitory hyperglycemia and did not present disturbances in insulin levels in the serum." (PMID 32150895, 2020). "Moreover, the absence of hyperglycemia is correlated with diminished NO levels in the pancreas of envenomed Il1r1−/− mice." (PMID 32150895, 2020).
injury (5 papers, 2006 to 2022). Damage inflicted on the body as the direct or indirect result of an external force, with or without disruption of structural continuity. "Moreover, it has been shown that IL-1 plays an important role in animal models of blast mediated traumatic brain injury, and a specific antagonist of IL-1R1 anakinra resulted in protection of RGCs function and restoration of GCL thickness." (PMID 36289519, 2022). "•Neuronal cholinergic IL-1R1 also mediate detrimental actions of IL-1 in brain injury." (PMID 30453020, 2019). "Our findings suggest that blocking IL-1 signaling via IL-1R1 may attenuate the activation of PAR-1 after brain injury." (PMID 16808851, 2006). "In vivo, microglia do not express IL-1R1 under basal conditions, although IL-1R1 is induced in hippocampal microglia following brain injury." (PMID 28668091, 2017).
multiple sclerosis (5 papers, 2015 to 2023). A progressive autoimmune disorder affecting the central nervous system resulting in demyelination. "The Il1r1 gene is broadly expressed, including the CNS, where IL-1R1 receptor signaling has been implicated in several neurodegenerative disorders such as Alzheimer’s, Parkinson’s and multiple sclerosis." (PMID 26930558, 2016). "Excessive IL-1R1 activation underlies a wide range of different CNS pathological conditions characterized by strong neuroinflammatory components such as AD, PD, ALS, multiple sclerosis, traumatic brain injury, Creutzfeldt-Jakob disease, HIV-1 encephalitis and age-related macular degeneration." (PMID 35163653, 2022).
renal fibrosis (5 papers, 2019 to 2025). A final common manifestation of a wide variety of chronic kidney diseases characterized by glomerulosclerosis and tubulointerstitial fibrosis. "To evaluate the function of tubular IL-1R in suppressing renal fibrosis by IL-1, we prepared renal proximal tubule–specific Il1r1-knockout mice." (PMID 40729113, 2025). "IL-1R1 has been significantly implicated in AKI as mice with global deletion of IL-1R1 are protected from ischemic and toxic AKI, renal fibrosis following unilateral ureteral obstruction (UUO), and cyst formation." (PMID 38693918, 2024).
Splenomegaly (5 papers, 2017 to 2025). Abnormal increased size of the spleen. "In these studies, deficiency for IL-1β or IL-1R1 attenuated bone marrow fibrosis and splenomegaly." (PMID 41298546, 2025). "Analysis of IkkeK38A/K38ATbk1fl/D135NCx3cr1-Crewt/tgIl1.18.33r-/- revealed that combined IL-1R1, IL-18R1 and IL-33R deficiency ameliorated splenomegaly, granulocytosis, and monocytosis, revealing an important role for IL-1, IL-18, and IL-33 in driving systemic inflammation in these animals." (PMID 38167258, 2024). "Here, we show that genetic deletion of IL-1 receptor 1 (IL-1R1) normalizes peripheral blood counts, reduces splenomegaly and ameliorates bone marrow fibrosis in homozygous Jak2V617F mouse model of myelofibrosis." (PMID 36100596, 2022). "Similar to the effects of IL-1R1 deletion, anti-IL-1R1 antibody treatment significantly decreased leukocytosis and splenomegaly and markedly reduced BM fibrosis in homozygous Jak2V617F mice." (PMID 36100596, 2022). "Furthermore, treatment with anti-IL-1R1 antibodies significantly reduces leukocytosis and splenomegaly, and ameliorates bone marrow fibrosis in homozygous Jak2V617F mice." (PMID 36100596, 2022).
Still’s disease (5 papers, 2011 to 2025). "Both conditions frequently respond well to IL-1β/IL-1R1-blocking drugs, which argues for excessive/dysregulated IL-1β signaling to play a central role in Still’s disease pathology." (PMID 38231276, 2024).
allergic asthma (4 papers, 2010 to 2024). A asthma with a basis in a pathological type I hypersensitivity reaction. "Supporting this, Th2 response and eosinophilic lung inflammation are significantly reduced in IL‐1β‐ and IL‐1R1‐deficient mice in a murine model of allergic asthma." (PMID 35988262, 2022). "The role of IL-1 in pulmonary immune responses in models of allergic asthma has been investigated using IL-1R1-deficient [IL-1R1 (−/−)] mice." (PMID 20671916, 2010). "Furthermore, the intranasal administration of PN has been shown to activate the MAPKs pathway and induce the production of TSLP and IL-25 independently of the IL-1R1/MyD88 signaling in a mouse model of allergic asthma." (PMID 39199175, 2024).
astrocytoma (4 papers, 2006 to 2025). "The interleukin-1 receptor (IL1R1) is a membrane protein which is variably expressed in different brain tumors and has also been suggested to play a role in brain immunotherapy of astrocytomas." (PMID 16842618, 2006).
Cachexia (4 papers, 2019 to 2022). Severe weight loss, wasting of muscle, loss of appetite, and general debility related to a chronic disease. "Consistent with prior studies, KxPxCx allograft-induced cachexia resulted in hypothalamic inflammation in vehicle-treated animals, with increases in expression of Selp, Il1b, Il1r1, Tlr7, Ccl2, and Icam1." (PMID 31615993, 2019). "In conclusion, the role of CRC cells is related to the production of classic cachexia-inducing factors (e.g., PIF, IL-6 and IL-6R, TNF-α, IL-1β, IL-1R1, and LIF), as well as novel factors known as “cachexokines”." (PMID 33557173, 2021).
dengue (4 papers, 2019 to 2024). "Having higher levels of ALOX-12 and PTAFR expression and lower levels of CCL6/MRP-1, CCL8/MRP-2, CCL12/MCP-5, and IL1R1 expression helps fight dengue." (PMID 38919218, 2024).
familial Mediterranean fever (4 papers, 2021 to 2025). Familial Mediterranean fever (FMF) is an autoinflammatory disorder characterized by recurrent short episodes of fever and serositis resulting in pain in the abdomen, chest, joints and muscles. "In patients with Familial Mediterranean Fever (FMF), miR-197-3p has been reported to modulate inflammation in monocytes and synovial fibroblasts by targeting the IL1R1 gene." (PMID 41009512, 2025).
glioma (4 papers, 2018 to 2025). A benign or malignant brain and spinal cord tumor that arises from glial cells (astrocytes, oligodendrocytes, ependymal cells). "While slight elevations of IL1R1 mRNA was noted in other gliomas as well, EPNs showed significantly higher expression levels (2 to 3 fold differences, p < 0.01)." (PMID 30464804, 2018). "We next analyzed IL1R1 expression in other aggressive CNS tumors such as adult and pediatric gliomas, CNS/PNETs and medulloblastomas." (PMID 30464804, 2018).